CD4 (CD4 molecule)
Diseases named in the same sentence as CD4 in open-access papers (continued):
Sharing a sentence is not in itself a finding about the gene and the disease.
smallpox (9 papers, 2011 to 2026). A condition that is caused by infection with Variola, and that is characterized by small, raised bumps. "C15, the B22 protein of ectromelia (murine model for smallpox), is known to target NK cells and CD4+ T cells, and, as shown here, also CD8+ T cells." (PMID 41674806, 2026). "Similar studies were launched to assess the presence and functionality of virus-specific CD4+ T cells as well as CD8+ T cells in recipients of smallpox vaccines or survivors of VARV infections." (PMID 36986285, 2023). "The cell-mediated immune response dependent on CD8+ T cells and CD4+ T cells as helper cells is induced after smallpox vaccination." (PMID 36986285, 2023). "Using different approaches, the long-term durability of memory CD4+ T cells to smallpox, over a period of many years, was an estimated t1/2 of ~10 years, which is also consistent with recent detection of SARS-CoV-T cells 17 years after the initial infection." (PMID 33408181, 2021). "Induction of such long-lived T cell responses is consistent with the finding that poxvirus-specific CD4+ T cells were detected decades after DryVax vaccination against smallpox." (PMID 24498312, 2014). "The results presented here show that human vaccinia specific CD4+ T cell clones that emerge following smallpox vaccination produce high levels of IL-13 in response to vaccinia and peptide stimulation." (PMID 21931646, 2011). "In addition, it has been shown that following smallpox immunization a small proportion of vaccinia specific CD4+ T cells produce exclusively IL-13 during the peak effector phase of the response (2 weeks following Dryvax vaccination)." (PMID 21931646, 2011). "To identify the factor responsible for CD4+ T cell inhibition by ECTV, we turned to the B22 family of proteins, named for the B22 open reading frame (ORF) in smallpox." (PMID 32745153, 2020). "In another study SIVmac251-infected rhesus macaques were vaccinated against smallpox: those with low CD4 counts failed to elicit neutralizing antibodies and succumbed to lethal monkeypox challenge, whereas those with normal CD4 counts elicited neutralizing antibody and survived a lethal challenge." (PMID 23402317, 2013).
strongyloidiasis (9 papers, 2009 to 2025). An infection that is caused by nematodes of the genus Strongyloides, most commonly Strongyloides stercoralis, which is a soil-transmitted helminth, and which is characterized by a variety of gastrointestinal, dermatologic, and, occasionally, pulmonary manifestations. "All of them were virologically suppressed and with good immunological status (>500 CD4+ cells/mmc) when diagnosed with strongyloidiasis." (PMID 41150371, 2025). "Additionally, LTBI individuals with Strongyloides stercoralis and S. mansoni had a decreased frequency of IFN-γ+CD4+ T cells and lower Th-1 cytokine responses to TB-antigen stimulation during Strongyloides infection that was reversed following anti-helminthic therapy." (PMID 36662839, 2023). "Those with strongyloidiasis had lower CD4+ cell counts (median 239; range 4–821) than those without the parasite (median 315; range 0–1757), but the difference was not significant (p = 0.16)." (PMID 21532747, 2011). "The median CD4+ and CD8+ T-cell count were similar in strongyloidiasis patients regardless of their HTLV-1 status." (PMID 19513105, 2009).
thymic carcinoma (9 papers, 2019 to 2023). Thymic carcinoma (TC) is a type of thymic epithelial neoplasm characterized by a high malignant potential. "Next, running flow cytometry using CD4 and CD8 markers is suggested to differentiate the lesion as mature thymic tissue from T lymphoblastic leukemia and thymic carcinoma." (PMID 35610708, 2022). "Its overexpression in advanced thymic carcinoma patients indicates its potential role in the pathogenesis of this malignancy, exerting negative modulation on cytotoxic CD8+ cells and promoting the activation of CD4+ regulatory T cells, thereby fostering self-tolerance and facilitating tumorigenesis." (PMID 37849766, 2023).
Zinc deficiency (9 papers, 2010 to 2024). A deficiency of the essential metal Zinc; an essential cofactor for many enzymes. "Normally, zinc deficiency leads to a decrease in CD4+ T cells and Th1/Th2 imbalance by impairing Th1 polarization." (PMID 34064626, 2021). "Previous results have indicated that zinc deficiency is associated with a decreased ratio of CD4+ to CD8+ cells and is indicative of cytotoxic immune response." (PMID 20546583, 2010). "Moreover, zinc is required for the regeneration of CD4+ T cells, and zinc deficiency is associated with significantly decreased CD4+/CD8+ ratio and lowered B cell numbers, which is similar to our findings." (PMID 24069198, 2013). "Lower levels may occur with any other micronutrient deficiency, zinc deficiency particularly, and could be a result of deficiency in a cohort of dietary nutrients whose effect could be on a number of host memory CD4 T cells generated in the course of infection." (PMID 35782946, 2022). "However, an in vitro differentiation study showed that TPEN-mediated zinc deficiency did not affect Th17 differentiation from naïve CD4+ cells, suggesting that Th17 activation mediated by zinc deficiency requires involvement of immune cells other than CD4+ cells." (PMID 32331308, 2020). "In general, both mature T cell types: CD4-expressing Th cells as well as CD8-expressing CTL, are affected by zinc deficiency." (PMID 29064429, 2017). "The mechanism is possibly due to reduction in T cell counts, as well as inhibition of IFN-γ expression in CD4+ T and CD8+ T cell induced by prenatal zinc deficiency." (PMID 24069198, 2013). "In the present study, we observed a significant decrease in the number of CD4+ T cells, CD4+/CD8+ ratio and a poor T cells proliferative response to HBsAg in vitro in prenatal zinc deficiency mice." (PMID 24069198, 2013). "Decreased B cell numbers and HBV-specific IgG production, together with reduced T cell proliferation, CD4+/CD8+ T cell ratio, and Th1-type immune response were observed in newborn mice whose mothers suffered from gestational zinc deficiency." (PMID 24069198, 2013). "A decrease in ratio of CD4+ to CD8+ was observed in the pups from zinc deficiency group, which was not corrected after supplementation with zinc during late pregnancy." (PMID 24069198, 2013). "We found that the offspring whose mothers had gestational zinc deficiency appeared to a markedly lower cellular and humoral immune response to HBV vaccine, characterized by lower IgG level, weaker T cell proliferation response, and lower expression of IFN-γ by CD4+ and CD8+ T cells." (PMID 24069198, 2013). "Additionally, HBsAg-specific cytokines analysis revealed that gestational zinc deficiency could inhibit secretion of IFN-γ from splenocytes, and decrease IFN-γ expression of CD4+ and CD8+ T cells." (PMID 24069198, 2013).
adenovirus infection (8 papers, 2010 to 2025). "Additionally, 85.71% of the patients had a significant decrease in the number of CD3+CD4+ T cells during the early stage, which suggests that adenovirus infection may cause immune system dysregulation." (PMID 35155471, 2021). "High levels of alemtuzumab exposure correlate with delays in CD4 + and CD8 + T cell recovery, which in turn increases the risk of CMV and adenovirus infections." (PMID 40622647, 2025). "The newly recruited intraepithelial CD4+ T cells are shown to play protective role in host defense against enteric adenovirus infection by producing protective IFN-γ and Granzyme B27." (PMID 39396665, 2025). "Low ranking female rhesus macaques (Macaca mulatta) had lower CD4+ and CD8+ lymphocyte counts than higher ranking females, and low ranking male longtailed macaques (Macaca fasicularis) were at greater risk of adenovirus infection than high ranking animals." (PMID 21143892, 2010). "Although we have not identified which cells produce IFNγ in the β-glucan model, it has been demonstrated by our group and others that following BCG vaccination, CD4+ T cells are the major source of IFNγ, whereas after pulmonary adenovirus infection, CD8+ T cells predominantly produce IFNγ." (PMID 40624927, 2025). "It was also shown that trained AMphs were programmed by respiratory adenovirus infection under direct contact with lung T CD8+ cells and in an environment rich in IFN-γ produced by T CD4+ cells." (PMID 39766307, 2024). "Compared with mild patients, the number of peripheral blood lymphocytes in children with severe adenovirus infection decreased significantly, especially the absolute counts of CD3+, CD4+, CD8+, and NK cells." (PMID 34960654, 2021). "Adenovirus infection increased the percentage of CD8+ T and CD4+ T cells that produce IFN-γ in the co-culture system." (PMID 34960654, 2021). "After 96 h of adenovirus infection, the cells were harvested and activated by TCR/CD4 co-aggregation." (PMID 27833610, 2016).
ANCA-associated vasculitis (8 papers, 2016 to 2025). "isolated CD4 and CD8 T cells, B cells, monocytes, and neutrophils from patients with SLE or ANCA-associated vasculitis (AAV) and performed microarray analysis in comparison with microarray analysis of whole PBMCs." (PMID 35663941, 2022).
atopic asthma (8 papers, 2010 to 2024). An asthma that is characterized by symptoms that are triggered by an allergic reaction caused by inhaled allergens such as dust mite allergen, pet dander, pollen and mold. "We thus concluded that the increase of circulating CCR7+ memory CD4+ T cells is a common feature of adult atopic asthma patients." (PMID 29507584, 2018). "We thus concluded that adult atopic asthma patients have an increase of circulating CD4+ T cells that are CD25+, FoxP3+, and CTLA-4+, FoxP3+CD25high, or FoxP3+CTLA-4+." (PMID 29507584, 2018). "We thus concluded that adult atopic asthma patients have increased CCR4+ CD4+ T cells in their blood and this increase is mainly due to the increase of CCR4+CD45RA−CD45RO+CCR7+ CD4+ T cells." (PMID 29507584, 2018). "We thus concluded that adult atopic asthma patients had a minor increase of circulating CRTH2+ CD4+ T cells and this increase was also mainly due to the increase of central memory CD4+ T cells." (PMID 29507584, 2018). "This study also provides evidence that the frequency of α4+ CD4+ T cells is clinically relevant in adult atopic asthma patients." (PMID 29507584, 2018). "In line with this, the difference in the frequency of CCR4+ CD4+ T cells between atopic asthma patients and control subjects was even greater when we compared them in Tcm cells." (PMID 29507584, 2018). "This study reports for the first time that an increase of long-lived CD4+ Tcm cells along with CCR4+ CD4+ Tcm cells is one of the major features of circulating blood T cells in adult atopic asthma patients." (PMID 29507584, 2018). "Current common therapeutics cannot alter the frequency of such CD4+ T cell subsets in adult atopic asthma patients." (PMID 29507584, 2018). "Our findings raise a fundamental question concerning the mechanisms responsible for the increased numbers of CCR4+ CD4+ Tem cells in atopic asthma patients." (PMID 29507584, 2018). "We report four major features of CD4+ T cells in the blood of atopic asthma patients." (PMID 29507584, 2018). "This increase of CCR4+ CD4+ Tcm cells can be seen across atopic asthma subtypes and severities." (PMID 29507584, 2018). "Another study in children with atopic asthma showed an increase in the percentage of CD4 and CD8 cells producing IL-4 and a decrease in CD4 cells producing IFNγ in comparison with healthy controls, while the percentage of cells producing TNF remained unchanged." (PMID 27799958, 2016). "Repeated inhalation of HDM allergen results in the activation of both innate and adaptive immunity characterized by recruitment of CD4+ Th2 cells, generation of specific IgE and infiltration of eosinophils into the airway, processes that typify the disease process in atopic asthma." (PMID 29922162, 2018). "In our study, we found that atopic asthma patients have more circulating CCR4+ CD4+ T cells and this was mainly due to the increase of CD4+ Tcm cells." (PMID 29507584, 2018). "Both atopic asthma patients and control subjects had similar frequencies of naïve (CD45RA+CD45RO−CCR7+) and CD45RA+CD45RO−CCR7− CD4+ T cells." (PMID 29507584, 2018). "Atopic asthma patients and control subjects had similar percentages of CD3+, CD3+CD4+, CD3+CD4+CD45RA+CD45RO− and CD3+CD4+CD8+ T cells in their blood." (PMID 29507584, 2018). "Compiled data from atopic asthma patients and control subjects indicated that atopic asthma patients have more CD45RA−CD45RO+CCR7+ CD4+ T cells than control subjects (left)." (PMID 29507584, 2018). "We found that atopic asthma patients and control subjects had similar percentages of CRTH2+ cells in CD4+ T cells (left) and CRTH2+CD45RO+ memory cells in CD4+ T cells (right)." (PMID 29507584, 2018). "Atopic asthma patients have a higher percentage of CRTH2+ cells, but this is only in the CD4+ Tcm cell compartment." (PMID 29507584, 2018).
atopic asthma (continued). "Understanding how ICOS regulates the development and the survival of EM CD4 cells may enhance novel vaccination strategies aimed at inducing protective EM CD4 T cells and regulatory strategies to control CD4 responses in diseases such as atopic asthma that are exacerbated by EM CD4 T cells." (PMID 21364749, 2011). "There is evidence that the number and function of two major subsets of Treg, namely, CD4+CD25+Foxp3+ Tregs and IL-10 producing Tregs, are impaired or altered in patients with atopic asthma compared with healthy individuals." (PMID 21197090, 2010). "In this study intracellular cytokine expression of IL-2, IL-4, IL-10, IL-13, IFN-γ, and TNF-α in CD4+ and CD8+ T cells in children with atopic asthma were measured by flow cytometry." (PMID 21197090, 2010). "In this study, however, we further found that atopic asthma patients have a significant increase in memory CD4+ T cells that express CCR7, but not CCR7− memory CD4+ T cells." (PMID 29507584, 2018). "CCR4+CCR7+ memory, but not CCR4+CCR7− memory, α4+, and CTLA4+ CD4+ T cells in patients show significant clinical implications in atopic asthma." (PMID 29507584, 2018). "It was also important to note that current therapy (i.e. corticosteroids, β-agonists, leukotriene inhibitors, and combinations thereof) was not capable of reducing the frequency of either total CD4+ Tcm or CCR4+ CD4+ Tcm cells in atopic asthma patients." (PMID 29507584, 2018). "In conclusion, atopic asthma patients and non-asthmatic control subjects have a similar frequency of α4+ CD4+ T cells." (PMID 29507584, 2018). "Atopic asthma patients have significantly more CD25+ CD4+ T cells than non-asthmatic control subjects." (PMID 29507584, 2018). "Atopic asthma patients also have significantly lower percentages of CD4+ and CD8+ T cells that expressed β7 integrin, but not CD11a." (PMID 29507584, 2018). "Taken together, we concluded that the frequency of CCR4+ CD4+ T cells, particularly CCR4+CD45RA−CD45RO+CCR7+ CD4+ T cells, varies among atopic asthma subtypes, but are not significantly influenced by corticosteroid or leukotriene inhibitor treatments." (PMID 29507584, 2018). "As such, we analyzed the frequency of CD4+ T cell subsets expressing CCR4 in atopic asthma patients and non-asthmatic control subjects." (PMID 29507584, 2018). "Accordingly, we found a significant increase of circulating CD45RA−CD45RO+ memory CD4+ T cells in atopic asthma patients, compared to non-asthmatic control subjects." (PMID 29507584, 2018). "It was also important to note that the absolute numbers of CD4+ Tcm cells were also greater in atopic asthma patients than non-asthmatic control subjects." (PMID 29507584, 2018). "Therefore, the increase of CD4+ Tcm cells in atopic asthma patients was not due to a decrease of CD4+ Tem cells in their blood." (PMID 29507584, 2018). "Furthermore, leukotriene inhibitors did not alter the percentage of CCR7+ memory CD4+ T cells in the blood of adult atopic asthma patients." (PMID 29507584, 2018). "Therefore, we concluded that adult atopic asthma patients have an increase of circulating CD45RA−CD45RO+CCR7+ T cells, but not CD45RA−CD45RO+CCR7− or CD45RA+CD45RO− CD4+ T cells." (PMID 29507584, 2018).
bladder urothelial carcinoma (8 papers, 2006 to 2025). "Our study indicates that m6A modification significantly affects the immune status of bladder urothelial carcinoma, where the collaboration between CD4+ T cells and B cells may play a crucial role." (PMID 38696324, 2024). "Additionally, intravesical bacillus calmette-guerin immunotherapy increased the CD4+ T cell population more effectively than intravesical chemotherapy.Studies showed that viruses, especially HPV, may be a risk factor for urothelial carcinoma of the bladder." (PMID 40079014, 2025). "Bladder urothelial carcinoma (BLCA) demonstrated significant distributions in its NK (p = 0.1718), CD4+ (p = 0.2715), and macrophage (p = 0.3333) cell scores." (PMID 36612301, 2023). "In the present study, tumour grade and Ki-67 labelling index were associated with increased tumour COX-2 expression and infiltration by CD4+ and CD8+ T-lymphocytes in patients with transitional cell carcinoma of the bladder." (PMID 17024120, 2006). "In urothelial bladder carcinoma and hepatocellular liver carcinoma, we observed positive correlations between the expression of C12orf75 and the infiltration of immune cells, including B cells, CD8+ T cells, CD4+ T cells, macrophages, neutrophils, and dendritic cells." (PMID 34074799, 2021).
cholestasis (8 papers, 2009 to 2025). Impairment of the bile flow caused by obstruction within the liver, or outside the liver in the bile duct system. "We then evaluated the infiltrations of monocytes and resting memory CD4 T cells, which were considered cholestasis-related, using CIBERSORT algorithm in GSE79850." (PMID 37229242, 2023). "In a mouse model of HBV infection, the HBV infection-related cholestasis caused a decrease in CD25+/CD69+ CD4+ and CD8+ cells, while CTLA-4+ CD4+ and CD8+ subsets were increased." (PMID 36678377, 2022). "Specifically, immune attack, CD4+T cell-mediated inflammation, abnormal autophagy, and imbalance of miR-506 trigger the apoptosis of bile duct epithelial cells, resulting in reduced bile ducts and cholestasis." (PMID 41409297, 2025). "Using flow cytometry, we did observe significant increases in the numbers of CD4 and CD8 positive T cells in the liver of mice infected by SA11 expressing RRV NSP1, suggesting that the bile duct obstruction is at least partly correlated with the infiltration of CD4 and CD8 positive lymphocytes." (PMID 39348381, 2024). "Furthermore, neutrophil depletion in turn restored the infiltration of total CD8+ T cells, total CD4+ T cells, and effector memory CD4+ T cells, together suggesting that liver metastasis induced by cholestasis mainly contributed to the neutrophils mediated immunosuppressive microenvironment." (PMID 38951890, 2024). "Results showed that increased resting memory CD4 T cells and reduced monocytes were observed in both PSC and PBC livers and were thus more likely to be involved in cholestasis." (PMID 37229242, 2023). "As such, CD4+ T cells and CD8+ T cells work independently to mediate neonatal bile duct obstruction, suggesting that these factors are potential therapeutic targets to stop the progression of bile duct obstruction." (PMID 35563229, 2022). "Moreover, an additional effect of cholestasis was confirmed by finding of positive correlation between AP in the serum and fraction of CD4+P+ cells, and negative correlation of both AP and bilirubin with fraction of P+ cells among CD8+ cells." (PMID 19436761, 2009). "Similarly, augmented proportions of TP+ cells, CD3+P+ cells and CD4+P+ cells were found in patients elected for OC, which preoperatively, had higher preoperative levels of CRP, AP, B, AST and ALT, suggesting that preoperative inflammation and cholestasis affected the perforin-related events." (PMID 19436761, 2009).